PLG (plasminogen)
Diseases named in the same sentence as PLG in open-access papers (continued):
Sharing a sentence is not in itself a finding about the gene and the disease.
tumor (continued). "Cells from rat carcinoma cell lines PROb (giving progressive tumours) and REGb (giving regressive tumours) have cell surface receptors which bind specifically rat plasminogen and plasmin." (PMID 1322156, 1992). "Furthermore, the expression level of ANXA2 in tumor cells affects the cytoskeletal composition and the plasminogen/plasmin system, playing a crucial role in tumor migration." (PMID 39350574, 2024). "Additionally, it supports tumor invasion by activating cathepsin L, which converts plasminogen into plasmin, leading to the degradation of key extracellular matrix proteins and activation of latent matrix metalloproteinases." (PMID 39439947, 2024). "Finally, tumor growth was also reduced in NSG mice subcutaneously or orthotopically implanted with patient‐derived PDAC tumor cells in which circulating plasminogen was pharmacologically reduced." (PMID 37971174, 2024). "Furthermore, both the wild-type mice treated with plasmin inhibitors and plasminogen-knockout mice had smaller metastatic tumor sizes and longer survival rates than untreated wild-type mice." (PMID 37190188, 2023). "However, the available data seem to describe a complex picture in relation to different MMP types: MMP-7 cleaves type-XVIII collagen to endostatin and plasminogen to angiostatin, thus potentially inhibiting angiogenesis and, consequently, tumor growth." (PMID 37445908, 2023). "A potentially clinically useful regulator of zymogen activation is also a monoclonal antibody that binds to the proenzyme of urokinase-type plasminogen activator (uPA), which is an enzyme that converts plasminogen to plasmin and is involved in tumor progression and metastasis." (PMID 38069440, 2023). "In addition, MMP-3 is generated from plasminogen and expressed in the peri-tumoral area to facilitate tumor growth and invasion." (PMID 36839884, 2023). "Previous research investigating the role of the plasminogen activation system on cancer progression has measured uPAR expression on excised tumor tissue, blood levels of urokinase-type plasminogen activator (uPA), and the various forms of uPAR and suPAR in circulation." (PMID 37875832, 2023). "Moreover, GP1 displayed increased expression of angiogenic features (e.g., ANGPTL4, EGFR, AAMP) and complement and coagulation cascade components (e.g., C1, C7, C8, C9, PLG, SERPINE1), which have been associated with aggravated tumor invasion." (PMID 35440542, 2022). "Furthermore, it resulted in an increase in plasminogen and a decrease in plasmin levels, which were increased by the tumor." (PMID 35371322, 2022). "Blocking csGRP78 with an anti-GRP78 antibody was shown to protect against the cell invasion of LoVo, a human colon adenocarcinoma cell line, indicating that csGRP78 may bind to plasminogen to promote tumor cell migration and invasion." (PMID 35625836, 2022). "Human and mouse uPA1-48 (huPA1-48 and muPA1-48), human and murine uPA1-48 fusion proteins (huPA1-48Ig and muPA1-48Ig), and human and mouse pegylated uPA1-48 (PEGh1-48 and PEGhm1-48) also inhibit tumour growth by inhibiting tumour stromal cell uPAR-dependent plasminogen activation." (PMID 35303878, 2022). "Among these, the cyclo[D-Cys19]-uPA19-31 was suggested as a promising possible drug in uPAR overexpressing tumor cells for its ability to inhibit uPA/uPAR interaction, disrupting uPA binding to uPAR and abrogating uPA plasminogen activation at the cell surface and fibrin degradation." (PMID 35158766, 2022). "As an activator of pro-uPA, uPAR binds to pro-uPA as well as the active uPA fragment and subsequently may enhance plasminogen conversion both locally at the invasive tumor front with uPAR and systemically with suPAR binding." (PMID 36174075, 2022). "This suggested that M. hyorhinis might act as a bridge to enhance the ability of tumor cells to capture plasminogen to their surface, thereby affecting the subsequent tumor development process." (PMID 34082810, 2021).
tumor (continued). "At the cell membrane, ENO1 activates the plasminogen system to accelerate tumor cell invasion." (PMID 33968941, 2021). "Additionally, both catecholamine release due to chronic stress and increased plasminogen synthesis due to aging have been shown to modulate angiogenesis and thereby support OvCa tumor growth." (PMID 33810259, 2021). "It is a plasminogen proteolytic fragment recovered from tumor-bearing mice." (PMID 34833950, 2021). "Urokinase plasminogen activator (uPA) interaction with its receptor, urokinase plasminogen activator receptor (uPAR), leads to proteolytic activation of plasminogen to plasmin, a broad-spectrum protease which enables tumour cell invasion and dissemination to distant sites." (PMID 34439251, 2021). "Plasminogen activation by uPA promotes tumor invasion in lung, breast, and ovarian cancer." (PMID 33810259, 2021). "CLEC3B encodes a tetranectin protein that is designated to the extracellular region, where it binds to plasminogen, and could be involved in tissue remodeling for tumor invasion and inflammation." (PMID 32545216, 2020). "Besides, dDAVP was reported to reduce tumor-induced angiogenesis in vivo by favoring the formation of angiostatin through the proteolytic cleavage of plasminogen." (PMID 32166534, 2020). "It is a proteolytic fragment of plasminogen that was isolated from tumor-bearing mice." (PMID 32489466, 2020). "Therefore, we postulate that K47 succinylation stabilizes S100A10 by inhibiting its ubiquitylation and subsequent proteasomal degradation, which enhances plasminogen activation and promotes tumour cell invasion and migration." (PMID 30394687, 2019). "The plasminogen activation has an important role in tumor invasion and metastasis." (PMID 31528642, 2019). "In addition PGK1, when secreted in extracellular compartment by tumor cells, binds plasmin thus permitting the cleavage of plasminogen in order to generate the vascular inhibitor angiostatin." (PMID 29995887, 2018). "ENO1 localized on the cell membrane can activate the plasminogen system as a fibrin soluble plasminogen receptor, and the plasminogen system can promote the invasion and metastasis of tumor cells through participation of basement membrane and extracellular matrix remodeling." (PMID 29483925, 2018). "The cancer invasion factor uPA was found to be positively correlated with numerous biomarkers in the tumor and/or HPN samples, including uPA, which is a known promoter of tumor invasion via the conversion of plasminogen to plasmin and the subsequent activation of procollagenases." (PMID 29774091, 2018). "It remains unclear whether the reduced tumor growth is due to the plasminogen‐dependent function of S100A10 or a novel intracellular function related to apoptosis or proliferation." (PMID 30009399, 2018). "Specifically, Pro-uPA secreted by tumor cells binds to uPAR to activate uPA, which then activates plasminogen bound to the cell surface, converting it into plasmin and degrading tumor cell connections, including laminin, fibrin, fibronectin, and other substrates." (PMID 30104473, 2018). "Moreover, we assumed that tumor budding, as the histomorphological correlate of epithelial-mesenchymal-transition (EMT), was also associated with the activity of the plasmin/plasminogen system." (PMID 28286517, 2017). "Using brain colonization assays via intracardiac injection of fluorescent tumor cells (by-passing intravasation of tumor cells), this study demonstrated that tumor cells express plasminogen inhibitors serpins, including serpin B2, in order to promote cancer cell survival and vascular co-option." (PMID 27048955, 2016). "Targeting TM by its antagonists, such as TM-specific antibodies or plasminogen kringle domains, may be useful to inhibit tumor angiogenesis and growth." (PMID 27602495, 2016).
tumor (continued). "Moreover, several studies have reported that this nicked β2-GPI is able to bind plasminogen and inhibits endothelial cell growth in vitro, and suppressed neovascularization and tumor growth in vivo." (PMID 27579889, 2016). "In cancer cells, enolase is overexpressed and localizes on their surface, where it acts as a key protein in tumor metastasis, promoting cellular metabolism in anaerobic conditions and driving tumor invasion through plasminogen activation and extracellular matrix degradation." (PMID 26401855, 2015). "In this regard the tumour specific induction of plasminogen is of great importance." (PMID 25872475, 2015). "However, elevated levels of uPA and other components of the plasminogen activation system are correlated with tumor malignancy." (PMID 26258071, 2015). "Therefore, matrix metalloproteinases (MMP) and the plasminogen/plasmin system cleave basement membrane components into multiple fragments released into the tumor microenvironment." (PMID 25668817, 2015). "The plasminogen system is involved in tumor growth, invasion and metastasis." (PMID 25860938, 2015). "Plasminogen activators (PA) stimulate the production of plasmin that in turn activates the fibrinolytic pathway and extracellular matrix degradation, leading to enhanced tumor cell migration." (PMID 26359694, 2015). "Plasminogen activation mediated by α-enolase plays important roles in several physiological and pathophysiological processes, including tissue remodeling, inflammatory response, pathogen invasion and metastasis of tumor cells." (PMID 25171719, 2014). "A growing body of evidence suggests that dysregulation of any of the PLG/PLA system components may result in tumor growth and metastasis formation." (PMID 25407528, 2014). "Finally, implantation of uPA competent T241 fibrosarcoma cells into Plg+/+ mice enhanced tumor growth and angiogenesis as compared to Plg−/− littermates further emphasizing the role of the PLG/PLA system in cancer biology." (PMID 25407528, 2014). "We propose that ENO1 links plasminogen with the uPA/uPAR complex in close proximity on tumor cells that express endogenous plasminogen, uPA, and uPAR, resulting in efficient generation of plasmin and subsequent proteolytic activity on the surface of tumor cells." (PMID 23894455, 2013). "Among serine proteases, the urokinase type plasminogen activator (uPA), which triggers a proteolysis cascade by accelerating the conversion of plasminogen into plasmin, is important for tumor invasiveness and metastasis and its expression is increased in solid tumors." (PMID 22246562, 2012). "Moreover, PLG, another RORα target gene displayed by the present study, is involved in fibrinolysis, wound healing, tumor growth and metastasis." (PMID 21818335, 2011). "Plasminogen, a single-chain glycoprotein of 92 kDa consisting of an N-terminal peptide, five kringle domains, and a serine protease domain, plays a crucial role in tumor metastasis and angiogenesis where localized proteolysis is required." (PMID 21787393, 2011). "In addition, S100A10 and Annexin A2 form isodimers, prompting the invasion and metastasis of the tumor by activating plasminogen." (PMID 19638242, 2009). "PLG (gene Hs.368912) has the potential to simultaneously regulate calcium signaling pathways and regulate pHi via an association with NHE3 linked to DPP IV, necessary for tumor cell proliferation and invasiveness." (PMID 17316436, 2007). "In both cases, however, administration of exogenous tPA improved anti-tumour activity, suggesting that the efficacy of the N-acetyl-cysteine treatment as reported by Agarwal may benefit from administration of exogenous plasminogen activators as well." (PMID 16753063, 2006). "In addition, highly sulfated GAGs, heparin and heparan sulfate, and sulfated polysaccharide, fucoidan, have been reported stimulating tumor cell invasion in vitro, due to a stimulation of the proteolytic cascade of plasminogen activation." (PMID 16111491, 2005).
tumor (continued). "Urokinase-like plasminogen activator (uPA), initially recognised by its ability to convert plasminogen to plasmin and to participate in the fibrinolytic cascade, is now considered to have a wider role, which encompasses metastatic invasion by tumour cells and liver regeneration." (PMID 15617575, 2004). "Components of the fibrinolytic system, such as plasminogen activators and inhibitors, are frequently overexpressed in aggressive cancers and serve as biomarkers of poor prognosis, and fibrin itself acts as a scaffold for tumor cells, providing structural support for cell migration and tumor growth." (PMID 40298646, 2025). "Furthermore, the plasminogen activation system operates through specific cell surface receptors like annexin A2/S100A10 complexes that can be delivered to distant organs via tumor-derived exosomes (or activated locally in the resident fibroblasts and immune cells)." (PMID 41463352, 2025). "Thus, a significant finding from these studies is that plasminogen deficiency or reduction significantly diminished KPC PDAC tumor growth but fibrinogen deficiency did not." (PMID 37971174, 2024). "The plasminogen cascade of serine proteases is involved in many different processes in many different tissues, primarily due to the ability of this system to regulate pericellular proteolytic activity, and dysregulation of this system results in tumor growth and metastasis formation." (PMID 28752190, 2017). "Thus, Bugge and colleagues reported that a deficiency of plasminogen in the mouse mammary tumor virus-Pym breast cancer model reduced spontaneous metastasis without affecting tumor growth." (PMID 25677449, 2014). "However, we have recently established that S100A10, and not annexin A2, is responsible for not only promoting the reported macrophage plasminogen-mediated matrix invasion and degradation but also the infiltration of tumor-promoting macrophages into tumor sites." (PMID 23519104, 2013). "Although the precise biological function of tetranectin in tumorigenesis is unknown, the protein likely has a role in cancer progression by enabling tumour cell invasion and metastasis through activation of the plasminogen-cascade and enhancement of the proteolytic processes." (PMID 20957082, 2010). "Active receptor-bound uPA in its turn activates the passage of plasminogen to plasmin, a strong proteolytic enzyme, which furthermore activates metalloproteinases, thus creating a localised microenvironment of matrix degradation, through which migration of tumour cells is facilitated." (PMID 12556966, 2003). "Immunohistochemical database analysis reveals that EIF4EBP1, RIMKLA, and BIRC5 are highly expressed in tumour tissues, while the PCK1, PLG, PEBP1, and CAT show a lower expression in tumour samples." (PMID 40591061, 2025). "Plasminogen binds to specific cell-surface receptors (including annexin II-S100A10, α-enolase, and uPAR) on endothelial cells, tumor cells, and immune cells within the lung microenvironment." (PMID 41463352, 2025). "Especially complex are processes involving cell adhesion and tumor invasion that include intricate interplay between uPAR, PAI1, uPA, and vitronectin, but also plasminogen and plasmin." (PMID 39859388, 2025). "Targeting the FABP1-PLG-PLAT axis inhibits fatty acid metabolic reprogramming and tumor angiogenesis by inhibiting fatty acid binding protein 1 (FABP1) and its downstream plasminogen (PLG) - tissue plasminogen activator (PLAT) signaling pathway." (PMID 41281744, 2025). "PLAU, a key component of the plasminogen-plasmin system, facilitates ECM degradation by activating plasminogen to plasmin, thus breaking down the basement membrane and enabling tumor cells to invade surrounding tissues." (PMID 41465316, 2025). "Collectively, these studies suggest that plasminogen promotes PDAC tumor growth and metastatic potential, in part through engaging plasminogen receptors on tumor cells." (PMID 37971174, 2024).
tumor (continued). "The Plasminogen (PLG), a blood zymogen produced and involved in anti-tumor growth because it inhibits angiogenesis." (PMID 39348357, 2024). "Together the patient tumour and cell line data prompted us to prioritize our investigation on the effects of ALDH1A3 on the plasminogen activation pathway and if this pathway contributes to ALDH1A3‐mediated invasion and metastasis in TNBC." (PMID 37753740, 2024). "Its ligand uPA catalyzes plasminogen to form plasminogen and produces a proteolytic cascade, which contributes to tissue remodeling and ECM decomposition, and creates favorable conditions for tumor invasion and metastasis." (PMID 37880277, 2023). "Among the various elements of the plasminogen system, urokinase plasminogen activator (uPA), its receptor (uPAR) and plasminogen activator 1 and -2 (PAI-1 and PAI-2) play a major role in tumor progression and metastasis." (PMID 35807785, 2022). "Here, we show that humanized anti‐Chi3L1 antibody attenuated tumor growth and metastasis in vivo via STAT6‐dependent PLG signaling and M2 polarization inhibition." (PMID 34861103, 2022). "A proteomics analysis of TCM showed that LRP-1 supports angiogenesis and tumor growth through the TGF-β signaling and plasminogen/plasmin system modulation, among others." (PMID 34680548, 2021). "This pathway, through the activation of the plasminogen system, degrades ECM, and consequently modulates tumor cell membrane protrusion, invasion, and motility." (PMID 32197509, 2020). "Since plasminogen activation plays a crucial role in tumor metastasis, and TEM8 expression is elevated in tumor endothelium, our findings reveal that TEM8 is a key molecule involved in tumorigenesis and progression." (PMID 30241478, 2018). "Angiostatin produced from plasminogen by MMP7 and MMP9 has been shown to have biological activities such as inhibition of endothelial cell proliferation, angiogenesis, tumor growth and metastasis." (PMID 24216994, 2013). "Cathepsin B had previously been shown to activate pro-uPA, a serine protease and member of the plasminogen cascade involved in ECM degradation, matrix metalloproteinase (MMP) activation, and tumor cell invasion." (PMID 22093547, 2011). "The activated serine protease uPA is able to convert plasminogen to plasmin, which in turn degrades the extracellular matrix (ECM) and leads to invasion and metastasis of tumour cells." (PMID 17663760, 2007). "For example, it has been suggested that the mechanism by which endothelial cell proliferation and tumour angiogenesis is inhibited is via the ability of MMP-7, -9, and -12 to convert plasminogen in to angiostatin." (PMID 17311017, 2007). "To learn more about the specific roles of each of the molecules of the urokinase plasminogen activation system, we modulated the expression of uPA, PAI1 and uPAR in two tumor cell lines by overexpression of uPA system molecules, cloned in plasmids and transfected into cells." (PMID 39859388, 2025). "Concurrently, plasminogen (PLG), a key regulator of proteolytic activity in the tumor microenvironment, may facilitate ammonia-mediated extracellular matrix remodeling through HIF-1-induced protease activation, further amplifying invasive potential." (PMID 40821775, 2025). "The plasminogen–plasmin system represents another crucial protease pathway in PMN development, as tumor cells utilize plasminogen receptor–plasminogen activator complexes to generate plasmin at specific times during PMN formation and in particular locations within the PMN." (PMID 41463352, 2025). "Plasminogen (PLG), a glycoprotein synthesized in the liver, is activated by plasminogen activators and is critically involved in proteolytic processes within the tumor microenvironment." (PMID 40821775, 2025). "Plg‐RKT reduction in tumor cells, but not reduced S100A10, suppressed metastatic potential in a manner that mimicked plasminogen deficiency." (PMID 37971174, 2024).